RN7SL47P (RNA, 7SL, cytoplasmic 47, pseudogene)
Gene: Miscellaneous RNA gene on chromosome 6 (106,283,413 to 106,283,711, reverse strand). Ensembl gene ENSG00000244710.
Homologues: Orthologues: chimpanzee Metazoa_SRP (98% identical), macaque Metazoa_SRP (90% identical). Paralogues in human: RN7SL2 (87% identical), RN7SL1 (86% identical), RN7SL3 (86% identical), RN7SL786P (84% identical), RN7SL509P (83% identical), RN7SL126P (82% identical), RN7SL357P (82% identical), RN7SL408P (82% identical), RN7SL664P (82% identical), RN7SL88P (82% identical), Metazoa_SRP (81% identical), RN7SL14P (81% identical), and 704 more.